RNASE6 (ribonuclease A family member 6)
Description:
Ribonuclease which shows a preference for the pyrimidines uridine and cytosine. Has potent antibacterial activity against a range of Gram-positive and Gram-negative bacteria, including P.aeruginosa, A.baumanii, M.luteus, S.aureus, E.faecalis, E.faecium, S.saprophyticus and E.coli. Causes loss of bacterial membrane integrity, and also promotes agglutination of Gram-negative bacteria. Probably contributes to urinary tract sterility. Bactericidal activity is independent of RNase activity.
Synonyms: RNS6; RAD1; RNaseK6
Tractability: Small molecule: a structure with a bound ligand is known. Antibody: UniProt places it where antibodies can reach, with high confidence; its Gene Ontology location is reachable by antibodies, with high confidence; UniProt predicts a signal peptide or a membrane-spanning region. PROTAC: its protein half-life has been measured.
Gene: Protein-coding gene on chromosome 14 (20,781,068 to 20,782,467, forward strand). Ensembl gene ENSG00000169413.
Subcellular location: Secreted; Lysosome; Cytoplasmic granule
Pathways (Reactome):
Immune System: Antimicrobial peptides
Gene Ontology:
Molecular function: RNA nuclease activity; nucleic acid binding
Biological process: antibacterial humoral response; antimicrobial humoral immune response mediated by antimicrobial peptide; defense response to Gram-negative bacterium; defense response to Gram-positive bacterium; defense response to virus; innate immune response; defense response; RNA catabolic process
Cellular component: cytoplasmic vesicle; extracellular region; lysosome
Genetic constraint (gnomAD): Loss-of-function variants: 1 observed, 0.68 expected, observed/expected ratio (o/e) 1.47, 90% interval 0.31 to 1.92. That is too few expected variants to judge how well the gene tolerates losing a copy. Missense variants: 197 observed, 191.4 expected, observed/expected ratio (o/e) 1.03, 90% interval 0.92 to 1.16. Synonymous variants: 64 observed, 67.89 expected, observed/expected ratio (o/e) 0.94, 90% interval 0.77 to 1.16.
Homologues: Orthologues: chimpanzee RNASE6 (99% identical), macaque RNASE6 (95% identical), rabbit RNASE6 (75% identical), pig RNASE6 (71% identical), guinea pig RAD1 (65% identical), mouse Rnase6 (64% identical), rat Rnase6 (63% identical), guinea pig RAD2 (49% identical). Paralogues in human: RNASE7 (54% identical), RNASE8 (53% identical), RNASE2 (45% identical), RNASE3 (44% identical), RNASE1 (33% identical), RNASE4 (33% identical), ANG (25% identical), RNASE10 (25% identical), RNASE9 (23% identical), RNASE11 (19% identical), RNASE12 (19% identical), RNASE13 (19% identical).
Diseases named in the same sentence as RNASE6 in open-access papers:
RNASE6 is named in the same sentence as 15 diseases in open-access papers, as found by Europe PMC text mining. Sharing a sentence is not in itself a finding about the gene and the disease. The quoted sentences say what the papers report.
atherosclerosis (1 paper, 2021). A disease characterized by the build-up of fatty material and calcium deposition in the arterial wall resulting in partial or complete occlusion of the arterial lumen. "We collected peripheral blood from healthy volunteers and patients with atherosclerosis, and the results of ELISA showed that the expression of Rnase6 was significantly up-regulated in the peripheral blood of patients." (PMID 34395402, 2021). "Next, methylation-specific polymerase chain reaction (MSP) was used to detect the methylation status of Rnase6 in peripheral blood of healthy volunteers and patients with atherosclerosis." (PMID 34395402, 2021). "However, the specific regulatory mechanism of Rnase6 in the process of atherosclerosis is still unclear and needs further exploration." (PMID 34395402, 2021). "In addition, promoting Rnase6 promoter methylation significantly inhibited the formation of plaque tissue and alleviated atherosclerosis in mice." (PMID 34395402, 2021).
diabetic nephropathy (1 paper, 2022). "Nevertheless, complete trials and more samples are needed to elucidate the mechanisms underlying the action of RNase6 in diabetic nephropathy." (PMID 36385487, 2022). "RNase6 was identified as the hub gene, closely associated with immune inflammatory damage in diabetic nephropathy." (PMID 36385487, 2022). "RNase6 and M1 macrophages, dendritic cells, monocytes, renal epithelial cells, and glomerular mesangial cells are associated to some extent in diabetic nephropathy." (PMID 36385487, 2022). "Our study identified RNase6 as a diagnostic and prognostic biomarker for diabetic nephropathy and found that it may play an essential role in the immunoinflammatory damage to the glomerulus." (PMID 36385487, 2022). "RNase6 has been identified as a key biomarker for the diagnosis and prognosis of diabetic nephropathy, providing a potential target and novel evidence for further research and treatment of diabetic nephropathy." (PMID 36385487, 2022). "RNase6 was identified as a novel biomarker for diabetic nephropathy, and detection of it may reflect glomerular immune inflammatory damage in DN, which may have guiding significance for future studies." (PMID 36385487, 2022). "Furthermore, RNase6 expression was negatively correlated with GFR, which is a prognostic and diagnostic indicator of diabetic nephropathy." (PMID 36385487, 2022). "Based on the analysis of single-cell sequencing data we can speculate that RNase6 is involved in the process of glomerular immunoinflammatory damage in diabetic nephropathy and that its role in the mononuclear phagocytic system should be equally valued." (PMID 36385487, 2022). "In addition, RNase6 expression was most positively correlated with macrophages M1 and conventional DCs, activated DCs, thus we speculate that it plays an essential role in the exacerbation of glomerular injury of diabetic nephropathy by the renal mononuclear phagocytic system." (PMID 36385487, 2022).
E. coli infection (1 paper, 2019). "In addition, Becknell and co-workers reported a regulation of RNase6 expression in macrophages in response to uropathogenic E. coli infection." (PMID 31312205, 2019).
esophageal squamous cell carcinoma (1 paper, 2020). Esophageal squamous cell carcinoma (ESCC) is a type of esophageal carcinoma (EC) that can affect any part of the esophagus, but is usually located in the upper or middle third. "The down-regulated RNASE6 might be a prognostic biomarker for esophageal squamous cell carcinoma." (PMID 33169786, 2020).
HIV-1 infection (1 paper, 2017). The type species of lentivirus and the etiologic agent of acquired immunodeficiency syndrome (AIDS). "The authors linked the downregulation of RNASE2, RNASE3 and RNASE6 to enhanced susceptibility of Th17 cells HIV-1 infection." (PMID 28241075, 2017).
osteosarcoma (1 paper, 2022). A usually aggressive malignant bone-forming mesenchymal neoplasm, predominantly affecting adolescents and young adults. "Therefore, our study indicates that the resting dendritic cell signature constructed by AOC3, CDK6, COL22A1, and RNASE6 may contribute to predicting osteosarcoma prognosis and thus therapy guidance." (PMID 36189307, 2022).
periodontitis (1 paper, 2022). An acute or chronic inflammatory process that affects the tissues that surround and support the teeth. "Additionally, RNASE6 was highly correlated with myeloid-derived suppressor cells (MDSCs) in periodontitis, and MANSC1 was highly correlated with plasmacytoid dendritic cells in PD." (PMID 36545026, 2022). "The results shwoed that RNASE6 gene was highly correlated with MDSC in periodontitis." (PMID 36545026, 2022). "The main findings of the current study identified five hub crosstalk genes (i.e., FMNL1, MANSC1, PLAUR, RNASE6, and TCIRG1) to be the linking mechanisms between periodontitis and PD." (PMID 36545026, 2022). "Five genes (i.e., FMNL1, MANSC1, PLAUR, RNASE6, and TCIRG1) were identified as crosstalk biomarkers linking PD and periodontitis." (PMID 36545026, 2022). "In periodontitis, MANSC1 was negatively correlated and the other four hub crosstalk genes (FMNL1, PLAUR, RNASE6, and TCIRG1) were positively correlated with five hub IRRGs, namely, AQP9, C5AR1, CD14, CSF3R, and PLAUR." (PMID 36545026, 2022).
pyelonephritis (1 paper, 2014). An inflammatory process affecting the kidney. "While RNase7 is significantly increased in relation to RNase6 in non-infected human bladder and kidney tissues, RNase6 expression significantly increases during pyelonephritis due to the influx of immune cells." (PMID 26029470, 2014).
Sepsis (1 paper, 2023). Sepsis is defined as life-threatening organ dysfunction caused by a dysregulated host response to infection. "Examples of genes related to this pathway that were differentially expressed in our sepsis samples include DEFA1, DEFA3, S100A8, S100A9 and RNASE6." (PMID 37731199, 2023).
infection (5 papers, 2015 to 2024). The state of being infected such as from the introduction of a foreign agent such as serum, vaccine, antigenic substance or organism. "BLaER1 cells, transdifferentiated into monocyte-like cells, as well as primary monocytes deficient for RNASE6 show a dampened TLR8-dependent response upon stimulation with isolated bacterial RNA (bRNA) and also upon infection with live bacteria." (PMID 39363059, 2024). "RNase 6 was shown to protect against urinary tract infections and RNASE6 transgenic mice showed increased protection against infection with uropathogenic Escherichia coli." (PMID 39363059, 2024). "The present time-course expression profiles in M. aurum infected THP1 macrophages indicates a downregulation of RNase3 and RNase6 after a short infection period followed by a significant upregulation at longer incubation times." (PMID 31312205, 2019). "This is the first structure-functional characterization of RNase6 antimicrobial properties, supporting its contribution to the infection focus clearance." (PMID 27089320, 2016).
bacterial infection (2 papers, 2017 to 2022). "Tissue distribution analysis showed that RNase6 was abundantly expressed in monocytes and neutrophils and that bacterial infection could induce the expression of this protein in vivo and exhibited antibacterial activity." (PMID 36385487, 2022). "Considering that RNase6 and RNase 7 expression is induced in macrophages upon bacterial infection, one might hypothesize that these antimicrobial proteins can also play a physiological role against intracellular dwelling mycobacteria." (PMID 29163551, 2017).
cancer (2 papers, 2019 to 2022). A tumor composed of atypical neoplastic, often pleomorphic cells that invade other tissues. "In this study, it is the first time to discover that the expression level of miR-515-5p is negatively related to the overall survival of ESCC, and miR-515-5p might control cancer cell progression through RNASE6 regulation." (PMID 32038997, 2019).
tumor (2 papers, 2019 to 2024). "On the other hand, immune system-related genes, including SLC16A10, RNASE1, and RNASE6, function in immune responses, antimicrobial activity, and enhancing anti-tumor immunity." (PMID 38461288, 2024). "The levels of eight genes (SPI1, RNASE6, C1QB, C1QC, CSF1R, C1QA, TBC1D2, and ATP6V0E1) expression were higher in tumor samples from UALCAN." (PMID 32038997, 2019).
RNASE6 also shares sentences with these, for which no sentence is quoted: colitis (1 paper); lung carcinoma (1).